KDM5C (lysine demethylase 5C)
Diseases named in the same sentence as KDM5C in open-access papers (continued):
Sharing a sentence is not in itself a finding about the gene and the disease.
renal cell carcinoma (7 papers, 2020 to 2024). "Inactivation of the KDM5C gene encoding for the histone demethylase protein JARID1C is frequent in renal cell carcinoma, and somatic KDM5C mutations have also been found in PC." (PMID 36900197, 2023). "Demethylation of H3K4me3 by KDM5C (JARID1C) leads to heterochromatin formation, and renal cell carcinoma patients with JARID1C mutations exhibit genome-wide DNA hypomethylation, increased genomic rearrangements, and an overall worse prognosis." (PMID 34017357, 2021). "In MSK-IMPACT cohort, renal cell carcinoma had the highest levels of KDM5C alterations (9.4%, 34/361)." (PMID 33953726, 2021). "In this pan-cancer analysis, the frequency of KDM5C alterations was 2.1% in a cohort of 45614 cancer patients, with esophagogastric cancer, endometrial carcinoma and renal cell carcinoma having the highest levels of KDM5C alterations, which was similar to previous publications." (PMID 33953726, 2021). "In addition, G6PD can also be upregulated via epigenetic perturbation (histone demethylase gene KDM5C depletion), which increases the flux of PPP to enhance NADPH and GSH synthesis to promote ferroptosis resistance in renal cell carcinoma (RCC)." (PMID 39061847, 2024). "Emerging evidence has found that histone demethylases (KDMs), the key regulators in histone modifications, such as KDM3A, KDM5C, KDM6A, and KDM6B, can promote renal cell carcinoma (RCC) progression via hypoxia-mediated angiogenesis pathways." (PMID 32092824, 2020).
colon cancer (4 papers, 2020 to 2024). "KDM5C has been implicated in promoting cancer cell proliferation in multiple cancer types, including breast, prostate, gastric, and colon cancer." (PMID 38425435, 2024). "For example, KDM5C promotes the proliferation of colon cancer cells through the FBXW7-c-Jun regulatory axis." (PMID 35248043, 2022). "Overexpression of KDM5c in human colon cancer cells leads to weakened FBXW7 transcription and increases c-Jun protein, resulting in the proliferation of colon cancer cells." (PMID 35248043, 2022). "In this study, we investigated the function and mechanism of KDM5c in colon cancer cell proliferation by disrupting KDM5c expression." (PMID 33042830, 2020). "Here, we report that overexpression of KDM5c in human colon cancer cells results in attenuated FBXW7 transcription and accumulated c-Jun protein, leading to increased proliferation of colon cancer cells." (PMID 33042830, 2020). "KDM5c expression in colon cancer was correlated with poor overall survival of patients in the first 7 years." (PMID 33042830, 2020). "Together, these results indicate KDM5c is an important determinant of colon cancer cell proliferation and cell cycle." (PMID 33042830, 2020). "Our study reveals novel roles of KDM5c in regulating colon cancer cell proliferation and suggests KDM5c as an attractive target for CRC treatment." (PMID 33042830, 2020). "Our results showed that KDM5c accelerated proliferation of colon cancer cells by down-regulating FBXW7 transcription, thereby, reducing c-Jun degradation via the ubiquitin-proteasome pathway." (PMID 33042830, 2020). "Specifically, KDM5c protein level can alter colon cancer cell growth by deregulating transcription of the cancer cell repressor gene FBXW7, thereby, modulating c-Jun degradation via the ubiquitin-proteasome pathway." (PMID 33042830, 2020). "KDM5c inhibits the multidrug resistance of colon cancer cell lines by down-regulating ABCC1." (PMID 35248043, 2022). "TCGA database analysis revealed high expression of KDM5c in colon cancer tissues." (PMID 33042830, 2020). "KDM5c plays an important role in controlling human colon cancer cell proliferation." (PMID 33042830, 2020). "Previous work has correlated KDM5c to various cancers, but whether KDM5c plays a role in colon cancer progression remains unknown." (PMID 33042830, 2020). "Consistent with this, KDM5c-KD obviously inhibited cell proliferation compared to the siControl group, suggesting that KDM5c has an important role in colon cancer cell proliferation, which has not been previously reported." (PMID 33042830, 2020).
colorectal cancer (4 papers, 2021 to 2025). A primary or metastatic malignant neoplasm that affects the colon or rectum. "This study aims to investigate the role of KDM5C in the progression of colorectal cancer (CRC) and explore the associated molecular mechanism." (PMID 38216914, 2024).
glioblastoma (4 papers, 2021 to 2026). The most malignant astrocytic tumor (WHO grade IV). "In the specific case of glioblastomas, these authors found proof of biallelic expression in females of KDM6A (encodes the lysine-specific demethylase 6A), KDM5C (encodes the lysine demethylase 5C), DDX3X (encodes a DEAD-box helicase 3 X-linked), and ATRX (encodes the ATRX chromatin remodeler)." (PMID 33752729, 2021). "To functionally investigate the impact of KDM5C overexpression on the BDNF and HIF1A levels, we transiently transfected the T98G glioblastoma cell line with KDM5C plasmid." (PMID 36142158, 2022).
kidney cancer (4 papers, 2014 to 2022). Primary or metastatic malignant neoplasm involving the kidney. "HIF increases KDM5C levels and activity, and the overall level of H3K4me3 is elevated when KDM5C is suppressed in VHL-defective kidney cancer cells." (PMID 30355451, 2018). "Therefore, the transcriptomes of tumor cells and infiltrating immune cells may be largely driven by founder variants in kidney cancer associated genes such as VHL and KDM5C." (PMID 35874919, 2022).
leukemia (4 papers, 2021 to 2025). A malignant (clonal) hematologic disorder, involving hematopoietic stem cells and characterized by the presence of primitive or atypical myeloid or lymphoid cells in the bone marrow and the blood. "To summarize, Kdm5c-KD primarily leads to the deregulation of differentiation-associated genes, tipping the balance towards a more immature leukemia with increased proliferative capacity." (PMID 36631623, 2023). "Under the same conditions, ETV6-RUNX1 expressed in hematopoietic progenitors readily induces leukemia if the mice are kept in a natural infection environment or if a second mutation (Kdm5c or Pax5 loss) occurs in close succession." (PMID 34336858, 2021). "A tumor suppressor role of KDM5C has also recently been reported in other leukemia subtypes." (PMID 40341256, 2025). "In wild-type leukemia cells, Kdm5c knockout increased H3K4me3 levels." (PMID 40341256, 2025). "Loss of Kdm5c may be involved in the leukemogenesis of ETV6/RUNX1+ ALL, but it is doubtful whether it is a main second hit driving leukemia, as in humans it has been only observed in a relapse sample." (PMID 34336858, 2021). "If the nature of the second hit confers tumor cell identity to ETV6-RUNX1+ leukemia, we hypothesized that ETV6-RUNX1+ B-ALLs triggered by the loss of either Pax5 or Kdm5c should differ from one another." (PMID 34336858, 2021). "Our discovery revealed that the histone demethylase KDM5C regulated the sensitivity of AML to Len, which might benefit the combination therapy for leukemia patients." (PMID 39881283, 2025).
lung cancer (4 papers, 2021 to 2025). A malignant neoplasm involving the lung. "Similarly, KDM5C has been observed to accelerate growth and metastatic dissemination of lung cancer cells through the epigenetic suppression of microRNA-133a." (PMID 38216914, 2024). "Additionally, EGFR, MGA, SMARCA4, ATM, RBM10 and KDM5C which are lung cancer related genes are mutated only in LUAD but not in LUSC." (PMID 33672117, 2021).
melanoma (4 papers, 2020 to 2021). A malignant, usually aggressive tumor composed of atypical, neoplastic melanocytes. "Additional roles in immune responses against cancer have been revealed for KDM5C and KDM6A in survival studies on human melanoma patients and may be linked to higher expression from X linked chromosomes." (PMID 34220955, 2021). "The LMC analysis also showed a strong relation of KDM5C expression to survival from melanoma." (PMID 32731355, 2020). "KDM5C and KDM6A have been previously shown to be preferentially expressed in primary melanoma in female patients and that the low levels of tumoral ATRX are associated with the progression of melanoma." (PMID 32731355, 2020). "The six pan-cancer X-linked genes (ATRX, CNKSR2, DDX3X, KDM5C, KDM6A, and MAGEC3) were examined for their association with melanoma survival by comparing the survival of all patients with the expression of genes above (high) or below (low) median expression levels." (PMID 32731355, 2020). "Three of these genes—KDM5C, KDM6A, and ATRX—are well-known epigenetic regulators with known tumor-suppressive functions in melanoma." (PMID 32731355, 2020).
acute myeloid leukemia (3 papers, 2016 to 2025). Acute myeloid leukemia (AML) is a group of neoplasms arising from precursor cells committed to the myeloid cell-line differentiation. "The primary acute myeloid leukemia (AML) cells and AML cell lines were used to explore the functions of histone demethylase KDM5C on the antileukemia effect of Len." (PMID 39881283, 2025).
autism spectrum disorder (3 papers, 2009 to 2023). A spectrum of developmental disorders that includes autism, and Asperger syndrome. "Based on the association between genetic variants in KDM5A, KDM5B, and KDM5C and ID and autism spectrum disorder (ASD), KDM5-interactors could potentially be implicated in neurological disorders." (PMID 36803422, 2023).
breast tumor (3 papers, 2021 to 2026). "TRIM11 deficiency in an animal model represses the growth of breast tumor and stabilizes KDM5C." (PMID 36192394, 2022). "Specifically, the expression of KDM5C was found to be significantly higher in clinical breast tumor samples than normal breast tissues." (PMID 33977073, 2021).
intrahepatic cholangiocarcinoma (3 papers, 2020 to 2025). A carcinoma that arises from the intrahepatic bile duct epithelium in any site of the intrahepatic biliary tree. "KDM5C was significantly downregulated in intrahepatic cholangiocarcinoma and served as a tumor suppressor by inhibiting cell proliferation, invasion, and fatty acid metabolism." (PMID 37185761, 2023). "However, the role of KDM5C in intrahepatic cholangiocarcinoma (ICC) remains unknown." (PMID 32714863, 2020).
memory impairment (3 papers, 2020 to 2022). "Additionally, Kdm5c knockout mice display behavioral deficits that are analogous to those exhibited by patients with pathogenic KDM5C variants, such as increased aggression, learning and memory impairments, and decreased seizure thresholds." (PMID 33729157, 2021).
meningioma (3 papers, 2020 to 2025). A generally slow growing tumor attached to the dura mater. "In addition, certain meningiomas harbor mutations in genes such as KDM5C, KDM6A, SMARCB1, and SMARCE1, which encode proteins involved in transcriptional chromatin remodeling (SMARCB1, SMARCE1) or histone demethylation (KDM5C, KDM6A)." (PMID 40787520, 2025). "In addition, nearly 10% of non-NF2 meningiomas harbor loss of function mutations of KDM5C and KDM6A, encoding histone lysine-specific demethylases, resulting in alterations in histone function and epigenetic regulation in meningiomas." (PMID 33194703, 2020). "Mutations of KDM5C (Lysine Demethylase 5C), KDM6A or Somatic SWI/SNF-related matrix associated actin-dependent regulation of chromatin subfamily B member 1 protein (SMARCB1) can lead to epigenetic modifications that are present in about 10% of non-NF2 meningiomas." (PMID 34679551, 2021).
microcephaly (3 papers, 2016 to 2024). A congenital or acquired developmental disorder in which the circumference of the head is smaller than normal for the person's age and sex. "Unlike individuals with KDM5B variants, individuals with KDM5C variants frequently present with profound verbal deficiency, short stature, spasticity, and microcephaly." (PMID 39202393, 2024).
pancreatic cancer (3 papers, 2022 to 2024). "For instance, whole-exome sequencing in human pancreatic cancers revealed truncating insertion and deletion mutations in the KDM5C gene." (PMID 38216914, 2024). "The results showed that the expression levels of KDM5A and KDM5C were negatively correlated with sensitivity to many pancreatic cancer-targeting or chemotherapeutic drugs, including axitinib and gemcitabine." (PMID 35493099, 2022). "This discovery provides strong evidence for the study of KDM5A and KDM5C as targets for new pancreatic cancer-targeting and chemotherapeutic drugs." (PMID 35493099, 2022). "We employed multiple public databases to reveal that the expression of KDM5A, KDM5B, and KDM5C (all members of the KDM5 family) is significantly increased in pancreatic cancer." (PMID 35493099, 2022). "In addition, previous studies have demonstrated that KDM5A and KDM5C are overexpressed in gemcitabine-resistant pancreatic cancer cells and that their expression is regulated by CD44, a stem cell marker linked to chemoresistance." (PMID 39239542, 2024). "Therefore, we speculate that KDM5C may also play the role of an oncogene in pancreatic cancer and expect it to become a new target for tumor therapy." (PMID 35493099, 2022).
Turner syndrome (3 papers, 2013 to 2022). Turner syndrome is a chromosomal disorder associated with the complete or partial absence of an X chromosome. "It has been previously suggested that X-linked genes escaping X-inactivation such as KDM5C are likely to be implicated in neurocognitive phenotypes of 45,X females with Turner syndrome, who in spite of normal cognitive abilities, frequently have problems in spatial reasoning and emotion recognition." (PMID 23356856, 2013). "Furthermore, the KDM5C-mutation associated targets identified here could play a role in Turner syndrome." (PMID 23356856, 2013). "Of the escape genes, SHOX, STS, KDM5C, KDM6A, UBA1, and RPS4X were associated with Turner syndrome." (PMID 36457060, 2022). "Since KDM5C escapes X-inactivation, we enriched our sample set by including 47,XXX, 47,XXY and 45,X (Turner syndrome) individuals." (PMID 23356856, 2013). "miR-320 is not an X-linked miRNA, but its expression is modulated by KDM5C, encoded by an XCI-escaping gene, which is also differentially expressed in Turner syndrome." (PMID 32356180, 2020).
Kabuki syndrome (2 papers, 2016 to 2018). Kabuki syndrome (KS) is a multiple congenital anomaly syndrome characterized by typical facial features, skeletal anomalies, mild to moderate intellectual disability and postnatal growth deficiency. "We tried to answer this question by supplying a large cohort of such diseases, including 44 patients with Kabuki syndrome that results from mutations in KMT2D (another regulator of the H3K4) to our classification model for KDM5C epi-signature." (PMID 29456765, 2018).
kidney tumors (2 papers, 2020 to 2021). "Next‐generation sequencing (NGS) analysis of the patient's renal tumor revealed the following heterozygous somatic alterations: FH (NM_000143 ‐ 1q43) intragenic deletion involving the loss of exon 1–2, KDM5C (NM_004187) exon 7 p.K289E (c.865A > G), and NUF2 (NM_031423) exon 8 p.S171C (c.512C > G)." (PMID 32463173, 2020).
lymph node metastasis (2 papers, 2022 to 2024). "In this study, we identified SECISBP2L (p = 2.20e-16, r = 1.000) and KDM5C (p = 0.00038, r = 0.690) as genes associated with lymph node metastasis." (PMID 35055428, 2022). "KDM5C expression was found to be positively correlated with lymph node metastasis and advanced tumor node metastasis (TNM) staging, while PFDN5 expression correlated negatively with both." (PMID 38216914, 2024). "The mutated genes associated with lymph node metastasis were SECISBP2L (p = 2.20e-16, r = 1.000) and KDM5C (p = 0.00038, r = 0.690); both of these showed a very strong association." (PMID 35055428, 2022).
metastatic tumors (2 papers, 2020 to 2022). "Other mutations included KDM5C (1/6, OVA_013), FLNA (1/6, OVA_378), RGS7 (1/6, OVA_047) and SPRY2 (1/6, OVA_365), which were also clonal in both primary and metastatic tumours." (PMID 32099096, 2020). "TRIM11 was also expressed higher in high metastatic tumors and KDM5C was lower expressed." (PMID 36192394, 2022).
nasopharyngeal carcinoma (2 papers, 2022 to 2023). A carcinoma arising from the nasopharyngeal epithelium. "The expression of KDM5C was elevated in nasopharyngeal carcinomas, and its silencing suppressed cell proliferation and colony formation, induced G1 cell cycle arrest, and significantly induced apoptosis, as well as reduced cell migration and invasion." (PMID 35326475, 2022). "Moreover, the expression of KDM5C was elevated in nasopharyngeal carcinomas." (PMID 35326475, 2022).
Stroke (2 papers, 2021 to 2024). Sudden impairment of blood flow to a part of the brain due to occlusion or rupture of an artery to the brain. "Our prior research has suggested that the X escapee genes Kdm6a and Kdm5c are involved in microglial activation after stroke in aged mice." (PMID 39399684, 2024). "We also examined the effect of Kdm5c’s signaling on stroke outcomes, and found the similar results as that of Kdm6a." (PMID 39399684, 2024). "All these data suggest that Kdm6a and Kdm5c signaling are pro-inflammatory after stroke in the aged." (PMID 39399684, 2024). "In these mechanistic studies, we found that KDM5C/6A is sexual dimorphically expressed in ischemic brain and that these two demethylases regulate the activation of microglia after stroke." (PMID 33712031, 2021). "The ratio of KDM5C+&Iba-1+ over Iba-1+ cells was significantly higher in the sham female vs. male brains, and the same pattern was seen in the stroke group." (PMID 33712031, 2021). "Although only an increase trend in the ratio was found in female vs. male control brains, the female stroke brains had significantly higher ratio than the male counterparts, indicating the ischemic stimuli amplified the sex difference in microglial expression of KDM5C/6A." (PMID 33712031, 2021). "The present study focused on two X chromosome escapee genes, Kdm6a and Kdm5c, and investigated their epigenetic modulation of IRF5/IRF4 via demethylation of H3K27Me3/H3K4Me3 in aged microglia after stroke." (PMID 39399684, 2024). "However, the mechanism by which Kdm6a/Kdm5c modulates IRF5/4 gene signaling and neuroinflammation after stroke is still elusive." (PMID 39399684, 2024). "Our data suggest Kdm5c’s detrimental effect on stroke injury is independent of IRF5 signaling." (PMID 39399684, 2024).
thyroid (2 papers, 2016 to 2024). "To clarify the role of KDMs in thyroid tumorigenesis, we next examined the mRNA expressions of KDM5C, KDM5D, and KDM6A by RT-PCR in a set of normal thyroid and tumor tissue samples from 77 patients, who underwent surgery for thyroid nodules." (PMID 38610938, 2024). "TCF12, KDM5C, IGF2BP3 and MAP4K3 mutations newly identified in our study might possibly be follicular tumor-specific thyroid mutations." (PMID 27626165, 2016).
Wiedemann-Steiner syndrome (2 papers, 2020 to 2021). Wiedemann-Steiner syndrome is a rare genetic condition characterized by distinctive facial features, hairy elbows, short stature, and intellectual disability. "Here, we show functional interactions of a writer-eraser duo, KMT2A and KDM5C, which are responsible for Wiedemann-Steiner Syndrome (WDSTS), and mental retardation X-linked syndromic Claes-Jensen type (MRXSCJ), respectively." (PMID 32483278, 2020).
Anxiety (1 paper, 2024). Intense feelings of nervousness, tension, or panic often arise in response to interpersonal stresses. "WNT3A-treated mice showed reduced anxiety levels based on the elevated-plus maze paradigm and marble-burying test, which indicated that transient WNT–β-catenin activation during embryonic brain development mimics the ID caused by KDM5C mutations." (PMID 38383780, 2024).